MIR4686 (microRNA 4686)
Synonyms: hsa-mir-4686
Safety:
Unwanted effects reported when the protein is acted on. In parentheses: how it was acted on, where the effect was seen, and who reports it.
opioid dependence (source: ClinPGx)
Gene: MicroRNA gene on chromosome 11 (2,173,063 to 2,173,138, forward strand). Ensembl gene ENSG00000265258.
Homologues: Orthologues: chimpanzee MIR4686 (100% identical).